SIRT3 (sirtuin 3)
Diseases named in the same sentence as SIRT3 in open-access papers (continued):
Sharing a sentence is not in itself a finding about the gene and the disease.
ischemic heart disease (9 papers, 2014 to 2025). "We observed a decline in SIRT1, SIRT3, and SIRT6 levels, broadly consistent with a ~50% reduction in SIRT1 reported in ischemic heart disease cohorts and a ~35% decline in SIRT3 under pressure-overload conditions." (PMID 41154755, 2025). "This highlights the vital role of SOD2 in ischemic heart disease therapy, governed by SIRT3 regulation." (PMID 39458930, 2024). "We advocate studying the role of SIRT1 and SIRT3 in ischemic heart disease populations to address future clinical usages and therapeutic options." (PMID 34216536, 2021). "Similar studies about Sirt3 regulating the quantity of anti-oxidants were also found in arterial thrombosis, traumatic brain injury, ischemic heart diseases, and so on." (PMID 34249264, 2021). "Our findings further suggest that augmentation of Sirt3 activity in stem cells may represent a novel therapeutic approach for the improvement of stem cell therapy for the ischemic heart diseases." (PMID 25192254, 2014). "Therefore, the dynamic network of SIRT1/SIRT3 acts as a mediator that regulates adaptive metabolic response to improve the tolerance of aged hearts to ischemic insults, which will facilitate investigation into the role of SIRT1/SIRT3 in age‐related ischemic heart disease." (PMID 37537789, 2023). "To investigate the critical role of SIRT1 and SIRT3 in aged‐related ischemic heart disease, we first evaluated the protein expression level of SIRT1 and SIRT3 in the young (4–6 months) and aged (24–26 months) male C57BL/6J mice left ventricle." (PMID 34216536, 2021). "In conclusion, NR provides significant cardioprotection against myocardial I/R injury by enhancing NAD+ levels and modulating the SIRT3/mtROS/JNK pathway, suggesting its potential as a novel therapeutic agent for ischemic heart diseases, meriting further clinical research." (PMID 39239543, 2024). "Lower serum SIRT3 levels have been detected in T2DM patients with coronary artery disease than in those without coronary injury." (PMID 37372041, 2023).
liver cancer (9 papers, 2012 to 2025). An epithelial or non-epithelial malignant neoplasm that arises from the liver. "Activators of SIRT3, such as Nicotinamide Riboside (NR) and Nicotinamide Mononucleotide (NMN), enhance SIRT3 activity, decrease lactylation levels, and inhibit liver cancer progression while sensitizing chemotherapy." (PMID 40166469, 2025). "MTS assay further confirmed that SIRT3 overexpression sensitized liver cancer cells to chemotherapeutic agents and sorafenib in SMMC-7721, Huh-7 and PLC/PRF/5 cell lines." (PMID 27367026, 2016). "MTS assay found that SIRT3 overexpression sensitized liver cancer cells to chemotherapeutic agents and sorafenib in SMMC-7721, Huh-7 and PLC/PRF/5 cell lines." (PMID 27367026, 2016). "Additionally, SIRT3-mediated de-lactylation of CCNE2 inhibits liver cancer cell proliferation, underscoring the regulatory role of lactylation in cell cycle control." (PMID 39868366, 2024). "Another mechanism for the tumor-suppression effect of SIRT3 in liver cancer is that SIRT3 could decrease ROS induced by hepatitis B virus x protein (HBx) after viral infection." (PMID 27483432, 2016). "However, the role of SIRT3 in drug sensitivity of liver cancer cells remains elusive." (PMID 27367026, 2016). "In this study, we found that SIRT3 decreased GSTP1 in both mRNA and protein levels which suggested SIRT3 regulated GSTP1, at least in part, occurs at a transcriptional level in liver cancer cells." (PMID 27367026, 2016). "Recent research has shown that nonhistone CCNE2 promotes liver cancer cell proliferation, migration, and invasion through lactylation, while NAD‐dependent deacetylase SIRT3 can remove CCNE2 lactylation, thereby regulating the cell cycle and impeding liver cancer progression." (PMID 40443721, 2025).
type 1 diabetes (9 papers, 2016 to 2025). "The study showed that the levels of sirtuin 1 and sirtuin 3 were lower in peripheral blood samples from patients with type 1 diabetes, T2D, or hypothyroidism than in healthy individuals." (PMID 35373529, 2022). "Moreover, a study demonstrated that melatonin can reduce mitochondrial oxidative stress while enhancing mitochondrial biogenesis to protect mitochondrial function, ultimately alleviating MI/R injury in type 1 diabetes via the AMPK-PGC1α-SIRT3 axis." (PMID 41019998, 2025). "In this study, we investigated whether partially disrupting NAMPT-mediated NAD+ biosynthesis or deleting SIRT3/SIRT5 would accelerate early neuroretinal dysfunction in the STZ-induced mouse model of type 1 diabetes." (PMID 30846716, 2019). "Therefore, we sought to determine whether combined deletion of both SIRT3 and SIRT5 may render mice more susceptible to retinal dysfunction in a model of type 1 diabetes." (PMID 30846716, 2019). "To test whether SIRT3 or SIRT5 exert a neuroprotective role under hyperglycemic conditions, we characterized whether germline deletion of Sirt3 or Sirt5 caused early neuroretinal dysfunction in a mouse model of type 1 diabetes." (PMID 30846716, 2019). "Moreover, SIRT3 and SIRT5 may have redundant roles in the inner retina and therefore possess the ability to functionally compensate for one another, as deletion of both was associated with modest, but significant, inner retinal dysfunction in the STZ-induced model of type 1 diabetes." (PMID 30846716, 2019). "Interestingly, further western blot data and immunohistochemistry staining showed that type 1 diabetes markedly down-regulated myocardial AMPK phosphorylation level and the expressions of PGC-1α, SIRT3 and SOD2." (PMID 28120943, 2017). "Therefore, the motivation behind this study was to test whether there was a neuroprotective role for metabolic regulation via NAMPT-mediated NAD+ biosynthesis, SIRT3, or SIRT5 in a mouse model of type 1 diabetes." (PMID 30846716, 2019). "The fact that monoallelic Nampt deletion did not accelerate retinal neurodegeneration in a mouse model of type 1 diabetes does not completely rule out the possibility that SIRT3 and SIRT5, downstream sensors of NAD+ availability, may still play a role in DR." (PMID 30846716, 2019).
amyotrophic lateral sclerosis (8 papers, 2013 to 2024). Amyotrophic lateral sclerosis (ALS) is a neurodegenerative disease characterized by progressive muscular paralysis reflecting degeneration of motor neurons in the primary motor cortex, corticospinal tracts, brainstem and spinal cord. "In a recent study, SIRT3 was able to rescue the mitochondrial fragmentation associated with a model of amyotrophic lateral sclerosis." (PMID 24046746, 2013). "In a model of amyotrophic lateral sclerosis (ALS), SIRT3 is able to prevent mitochondrial fragmentation of spinal cord motor neurons transfected with SOD1G93A." (PMID 27686535, 2017).
brain injury (8 papers, 2016 to 2023). Acute and chronic (see also brain INJURIES, CHRONIC) injuries to the brain, including the cerebral hemispheres, CEREBELLUM, and brain STEM. "Recent in vivo and in vitro experiments have demonstrated that SIRT3-mediated autophagy plays an important protective role in ischaemic brain injury." (PMID 37009480, 2023). "Whether SIRT3-Foxo3a-induced autophagy can produce the same effect in brain injuries remains unknown." (PMID 37009480, 2023). "Sirtuin-3 has been discovered as a key player for achieving the neuroprotective role of fucoidan by managing these pathways, whose ultimate goal is retrieving the entirety of the antioxidant response and preventing apoptosis of neurons, thereby averting neurodegeneration and brain injuries." (PMID 32380741, 2020).
endotoxemia (8 papers, 2013 to 2024). "Furthermore, simultaneous deletion of both SIRT2 and SIRT3 influences the metabolism and inflammatory responses of macrophages, while providing protection against endotoxemia; however, a single deficiency in either SIRT2 or SIRT3 has minimal or no impact on antimicrobial innate immune responses." (PMID 39372420, 2024). "One previous study examined the role of SIRT3 in various infection models, namely, endotoxemia, Escherichia coli peritonitis, Klebsiella pneumoniae pneumonia, listeriosis, and candidiasis." (PMID 35215060, 2022). "We then analyzed the impact of SIRT3 deficiency in a panel of severe and non-severe models of endotoxemia, peritonitis, pneumonia, listeriosis and candidiasis." (PMID 28634345, 2017). "Going well along with these observations, SIRT3 deficiency has no major impact on cytokine production, bacterial burden and survival of mice subjected to endotoxemia, Escherichia coli peritonitis, Klebsiella pneumoniae pneumonia, listeriosis and candidiasis of diverse severity." (PMID 28634345, 2017). "As a first approach, we tested a model of endotoxemia, which revealed that cytokine response and survival rates were not different in SIRT3+/+ and SIRT3−/− mice." (PMID 28634345, 2017). "Interestingly, SIRT3/5−/− mice were not more resistant to mild listeriosis than their wild type counterparts, and behaved like wild type mice in a model of endotoxemia." (PMID 31632409, 2019).
kidney injury (8 papers, 2018 to 2025). Trauma to the kidney. "By investigating the impact of CsA on mitochondrial function and exploring the effects of SIRT3 modulation, we sought to uncover the potential of SIRT3 as a therapeutic target for mitigating CsA-induced kidney injury." (PMID 38698042, 2024). "Targeting SIRT3 can effectively reduce mitochondrial fragmentation, reduce the degree of renal damage, and accelerate the recovery of renal function, suggesting that SIRT3 could promote recovery from kidney injury by maintaining the stability of mitochondrial structure and function." (PMID 34518519, 2021).
lymph node metastasis (8 papers, 2014 to 2025). "Multivariate analysis demonstrated that lymph node metastasis, the tumor size, and SIRT3 expression were independent prognostic factors for NSCLC patients." (PMID 28947845, 2017). "The SIRT3 level was correlated significantly with lymph node metastasis and clinical stage of NSCLC patients." (PMID 28947845, 2017). "In final part of present study, we observed a strong association between SIRT3, SIRT4, MTUS1 and OGG1-2a gene expression and lymph node metastasis." (PMID 26785117, 2016). "Moreover, univariate analysis showed that the expression of SIRT3, tumor size, lymph node metastasis, degree of differentiation, and clinical stage were correlated with the prognosis of NSCLC patients." (PMID 28947845, 2017). "Furthermore, SIRT3 expression was correlated with lymph node metastasis and clinical stage." (PMID 28947845, 2017). "This is the first meta-analysis focused on the association between SIRT3 expression and patient clinicopathological outcomes including survival, cancer/non-cancer tissues, lymph node metastasis, pathological differentiation, tumor stage, tumor size, and gender." (PMID 27483432, 2016). "In this study, we found that the expression level of SIRT3, the presence or absence of lymph node metastasis, and the tumor size were independent predictors of survival time." (PMID 28947845, 2017). "The meta-analysis suggested that SIRT3 overexpression was also not correlated with lymph node metastasis in total effect analyses (OR = 1.64, 95% CI = 0.80–3.39, P = 0.18)." (PMID 27483432, 2016).
neuroblastoma (8 papers, 2008 to 2025). Neuroblastoma (NB) is the most common solid, extracranial childhood tumor. "We also showed that ELF-MF-exposed neuroblastoma cells exhibit activation of sirtuin 3 expression, and SIRT3-dependent signaling has been recently linked to cancer metastatic development, through the improvement of mitochondrial integrity and fitness in response to oxidative proteotoxic stress." (PMID 29527520, 2018). "Overexpressing Mfn2 increased ATP production and activated Sirt3 in mouse neuroblastoma N2a cells." (PMID 35386849, 2022). "To elucidate the role of the AMPK/Sirt3 pathway in mediating RSV's neuroprotective effects, we conducted in vitro experiments using mouse neuroblastoma N2a cells." (PMID 40074082, 2025). "We formerly demonstrated that 2-ME decreases mitochondrial membrane potential in SH-SY5Y neuroblastoma cells and inhibits mitochondrial biogenesis by regulating PGC-1α, COXI, and SIRT3 as a result of the nuclear recruitment of nNOS and NO generation in 143B osteosarcoma cells." (PMID 36290736, 2022). "When neuroblastoma SH-SY5Y cells were exposed to CM of rAD-MSCs, cytotoxicity and ROS generation were reduced, through the upregulation of the antioxidant enzyme sirtuin 3 (SIRT3)." (PMID 32392722, 2020). "Expression of SIRT3 promotes apoptosis in neuroblastoma cells and enhances HCA lethality, whereas SIRT6 does not induce HT-22 cell death." (PMID 19116652, 2008). "We next examined whether the effects observed with SIRT1, SIRT2, SIRT3, SIRT5, and SIRT6 on the regulation of LK-induced neuronal death extended to mouse HT-22 cells, a hippocampally-derived neuroblastoma cell line." (PMID 19116652, 2008).
oral squamous cell carcinoma (8 papers, 2011 to 2024). "Our data were consistent with a model in which reduction in SIRT3 enzymatic activity associated with the V208I mutation plays a pathogenic role in oral squamous cell carcinoma." (PMID 23800187, 2013). "A sequence analysis conducted with OSCC patients demonstrated that variability in the SIRT3 gene was correlated with increased susceptibility for developing oral squamous cell carcinoma." (PMID 23800187, 2013). "Our findings provide a valuable insight into the potential role of SIRT3 in the development of oral squamous cell carcinoma, by showing that a non-synonymous point mutation in SIRT3 contributes to reduced catalytic activity of the protein and affects redox balance in OSCCs." (PMID 23800187, 2013). "Because exogenously expressed WT SIRT3 produced inhibition of cell growth in OSCC cell lines, we tested whether variability in the SIRT3 gene was correlated with increased susceptibility for developing oral squamous cell carcinoma." (PMID 23800187, 2013). "However, the sample size of this study was small, and a larger number of OSCC patients must be evaluated for SIRT3 mutation to reach definitive conclusions about the role of this gene in the development of oral squamous cell carcinoma." (PMID 23800187, 2013). "On the contrary, SIRT3 is overexpressed in oral squamous cell carcinoma (OSCC), and down-regulation of it inhibited OSCC cell growth and proliferation in vitro and in vivo." (PMID 27367026, 2016). "Nevertheless, overexpression of SIRT3 was correlated to the incidences of oral squamous cell carcinoma (OSCC) and downregulation of SIRT3 improved the sensitivity of OSCC to radiation and chemotherapy at the same time." (PMID 25105144, 2014). "In this study, we demonstrated that SIRT3 regulates cellular ROS, and this regulation has important implications for the growth of oral squamous cell carcinoma cells." (PMID 23800187, 2013). "In this study, we began to investigate the potential role of SIRT3 in regulating cellular redox balance in oral squamous cell carcinoma and studied how SIRT3 is involved in oral carcinogenesis." (PMID 23800187, 2013). "We found that increased activity SIRT3 in oral squamous cell carcinoma contributes to decreased ROS levels and increased cell proliferation." (PMID 23800187, 2013). "We found that compared with normal human oral keratinocytes (HOK), SIRT3 is highly expressed in oral squamous cell carcinoma (OSCC) cell lines, but the enzymatic deacetylation is significantly reduced." (PMID 23800187, 2013). "In addition, Sirt3 inhibitor LC-0296 was developed to target overexpressed Sirt3 in oral squamous cell carcinoma (OSCC)." (PMID 38474697, 2024). "Taken together, these data indicate that SIRT3 may function as a tumor suppressor in OSCC cell lines by regulating cellular ROS levels and decreasing SIRT3 activity, and also may increase susceptibility to the development of oral squamous cell carcinoma." (PMID 23800187, 2013). "In oral squamous cell carcinoma (OSCC) cell lines, downregulation of SIRT3 inhibited OSCC cell growth and proliferation and increased OSCC cell sensitivity to radiation and cisplatin treatments in vitro." (PMID 25105144, 2014). "The expression levels of all sirtuins in several oral squamous cell carcinoma (OSCC) cell lines were compared with normal human oral keratinocytes and observed that SIRT3 was highly expressed." (PMID 21472714, 2011). "However, to our knowledge, the role of SIRT3 in regulating antioxidant defenses has not been investigated in oral squamous cell carcinoma." (PMID 23800187, 2013).
osteosarcoma (8 papers, 2012 to 2025). A usually aggressive malignant bone-forming mesenchymal neoplasm, predominantly affecting adolescents and young adults. "In HEK293T and human osteosarcoma cells, SIRT3 downregulation increased the acetylation of the OSCP and alpha subunits of complex V, and this was associated with decreased activity and ATP levels." (PMID 30131726, 2018). "Several groups have reported that SIRT3 physically interacted with the OSCP subunit in human osteosarcoma cells, HEK293T cells, and HCT116 cells." (PMID 30131726, 2018). "After H2O2–induced oxidative stress, the SIRT3 gene was downregulated in osteosarcoma cybrids with the J haplogroup compared to H cybrids." (PMID 24919117, 2014). "The effects of silencing of the nuclear SIRT1 vs. the mitochondrial SIRT3 and SIRT5 family members on cell viability were analyzed in the human osteosarcoma (U2OS) and mesothelioma (Mero-14 and REN) cell lines." (PMID 31608237, 2019). "In invasive cancers like osteosarcoma, aberrant mitochondrial dynamics can be effectively suppressed by 2‐methoxyestradiol through modulating key regulatory pathways including PGC‐1α, Cyt c oxidase I (COXI), and sirtuin 3 (SIRT3), thereby interrupting cancer stem cell propagation." (PMID 40502813, 2025).
infertile (7 papers, 2020 to 2025). "The clinical implication of these observations is that the vicious sequence of SIRT 1 and SIRT3 deficiency, oxidative stress and telomere shortening needs to be broken in infertile patients if their reproductive capacity is to be regenerated successfully." (PMID 38255792, 2024). "Comprehensive exploration and targeted research on SIRT3 will continue to illuminate its multifaceted contributions to reproductive success and inform the development of innovative treatments for infertility." (PMID 39329773, 2024). "Recently, it has been shown that SIRT1 and SIRT3 proteins are inversely correlated with oxidative stress biomarkers and sperm DNA fragmentation in infertile patients." (PMID 38255792, 2024). "In addition, considering that previous studies were based on classic stress markers, the main strength of the present study is that the levels of a novel regulator (SIRT3) were evaluated in infertile patients with endometriosis who underwent an IVF cycle." (PMID 41009667, 2025). "Evidence from the literature suggests that SIRT3 levels are variable and respond adaptively to different stress conditions, making it a promising target for therapeutic interventions aimed at improving reproductive outcomes in women facing infertility challenges." (PMID 39329773, 2024). "The present study showed that the induction of PCOS reduced the expression of Sirt3 in oocytes, showing one of the mechanistic pathological features of PCOS in the development of infertility." (PMID 33841532, 2020). "ROC curve analysis of serum parameters showed that relative reactivities of CLU glycans with SNA and MAA, together with SIRT3 and FRAP concentrations, may be useful in the differentiation of infertile men with abnormal as well as normal semen parameters." (PMID 36142505, 2022).